EGFL7 (EGF like domain multiple 7)
Diseases named in the same sentence as EGFL7 in open-access papers (continued):
Sharing a sentence is not in itself a finding about the gene and the disease.
colorectal cancer (8 papers, 2015 to 2024). A primary or metastatic malignant neoplasm that affects the colon or rectum. "High tumor expression of epidermal growth factor-like domain 7 (EGFL7) has been associated with a poor prognosis in colorectal cancer." (PMID 28539619, 2017). "miR-221 demonstrated oncogenic potential in melanoma and, as shown here in colorectal cancer cells, targeted the tumor repressor AP2a, which regulates Egfl7 and miR-126 expression in colon epithelial cells." (PMID 39419989, 2024). "Studies indicate EGFL7 as an important gene in controlling angiogenesis and cancer growth, including in colorectal cancer (CRC)." (PMID 37957249, 2023). "However, the evidence on EGFL7 in colorectal cancer (CRC) is still very sparse." (PMID 25592646, 2015). "In colorectal cancer, SMYD2 increases RNA-binding activity via the monomethylation of K422 on HNRNPK, thereby influencing the stability of EGF-like domain multiple 7 (EGFL7) mRNA." (PMID 39482529, 2024). "In the colorectal cancer cell lines LOVO and SW480, PF increased caspase-dependent apoptotic cell death by regulating invasion, migration, proliferation, and colony formation and by inhibiting the TLR4/NF-kB axis and EGFL7." (PMID 38140352, 2023). "Overall and recurrence-free survival was not different between low and high expression of EGFL7 in colorectal cancer." (PMID 37957249, 2023).
gastric cancer (8 papers, 2014 to 2025). A primary or metastatic malignant neoplasm involving the stomach. "The differential expression of EGFL7 in several cancers was associated with epigenetic modification, involving malignant pleural mesothelioma, gastric cancer, and esophageal squamous cell carcinoma." (PMID 30953521, 2019). "EGFL7 was mainly located in the cytoplasm, and positive expression was detected in 96.2% of gastric cancer samples (76/79)." (PMID 24945379, 2014). "In our previous study, high expression of EGFL7 was found to correlate positively with the invasion and metastasis of gastric carcinoma." (PMID 24945379, 2014). "We previously demonstrated that EGFL7 is also overexpressed in gastric carcinoma, and expression was significantly correlated with pathologic characteristics, clinical progression, poor prognosis, and metastasis." (PMID 24945379, 2014). "Furthermore, EGFL7 is reported to be epigenetic modified in gastric cancer and esophageal squamous cell carcinoma." (PMID 30953521, 2019). "It has been reported that MALAT1 associates with EZH2 and enhanced methylation of H3K27 to downregulate genes in renal cancer cells; on the other hand, MALAT1 upregulates EGFL7 by altering the level of H3 histone acetylation at EGFL7 promoter in gastric cancer." (PMID 29511340, 2018). "Indeed, previous studies have shown that high EGFL7 expression promotes infiltration and metastasis of gastric carcinoma." (PMID 24945379, 2014). "We found that EGFL7 was overexpressed in multiple human gastric cancer (GC) cell lines and that overexpression promoted cell invasion and migration as revealed by scratch wound and transwell migration assays." (PMID 24945379, 2014). "It has been reported that gastric cancer (GC) cells, liver cancer (HCC) cells, and pituitary adenocarcinoma cells have considerably improved migration and invasion capabilities because of the overexpression of EGFL7." (PMID 33391349, 2020). "However, whether EGFL7 actually does enhance EMT and promote gastric cancer metastasis has yet to be determined." (PMID 24945379, 2014).
glioblastoma (7 papers, 2017 to 2024). The most malignant astrocytic tumor (WHO grade IV). "Increased levels of EGFL7 have been linked to increased dissemination of several tumors and to a reduced median patient survival time in glioblastoma patients." (PMID 30065025, 2018). "Increased NFAT5 activity enhanced glioblastoma cell-driven angiogenesis by mediating secretion of EGF like domain multiple 7 (EGFL7) via the miR-S38-3p axis." (PMID 39152497, 2024). "Moreover, NFAT5 cpuld also promote glioblastoma cell-driven angiogenesis through EGFL7 which was mediated via SBF2-AS1 and miR-338-3p." (PMID 32863773, 2020). "For instance, ECs of glioblastoma (GBM) blood vessels express high levels of EGFL7 that binds, impairs the endocytosis, and promotes the accumulation of αvβ3 (and α5β1) integrin on the surface of ECs72." (PMID 34131655, 2021).
acute myeloid leukemia (6 papers, 2019 to 2022). Acute myeloid leukemia (AML) is a group of neoplasms arising from precursor cells committed to the myeloid cell-line differentiation. "For instance, EGFL7 is highly expressed, and its high expression associates with lower complete remission rates in acute myeloid leukemia (AML) patients." (PMID 34635968, 2022). "EGFL7 caused acute myeloid leukemia (AML) blast proliferation." (PMID 33804387, 2021). "Among these gene, EGFL7 has been shown to play a role previously in the pathogenesis of Acute Myeloid Leukemia (AML) and hematopoiesis and is also known to be overexpressed in ETV6-RUNX1 leukemia." (PMID 33708624, 2021). "In acute myeloid leukemia, a hematopoietic blood cell cancer, recombinant EGFL7 inhibited DELTA-like 4-mediated Notch activation while anti-EGFL7 in combination with Dll4 increased Notch activation and induced apoptosis." (PMID 33804387, 2021).
colon carcinoma (5 papers, 2019 to 2024). "High tumor expression of EGFL7 (epidermal growth factor-like domain 7) has been associated with poor prognosis in colon cancer, and this gene was also selected." (PMID 38790260, 2024). "We also analyzed whether PF could inhibit the proliferation and metastasis of ulcerative colitis-associated colon cancer by targeting EGFL7." (PMID 36072982, 2022). "We further examined the expression of EGFL7 in the colon cancer tissues of patients, where EGFL7 is overexpressed relative to the normal colon tissue, and the results are consistent with the CAC mice." (PMID 36072982, 2022). "We detected the expression of EGFL7 mRNA in different groups of colon cancer SW480 cells by RT-qPCR." (PMID 36072982, 2022). "EGFL7 is positively correlated with the malignancy of colon cancer cells, and at the cell level, we also confirmed that the expression of EGFL7 is related to the proliferation, invasion, migration, clone formation, and apoptosis of colon cancer cells." (PMID 36072982, 2022). "We also analyzed the overall survival of colon cancer patients with different EGFL7 expression levels." (PMID 36072982, 2022). "The survival time of colon cancer patients with overexpression of EGFL7 is significantly lower than that of colon cancer patients with low expression of EGFL7." (PMID 36072982, 2022). "We compared the expression level of EGFL7 between different colon cancer cells and normal colon cells by RT-qPCR." (PMID 36072982, 2022). "The aim of this study was to analyze the ability of miRNA-126 and EGFL7 to predict disease recurrence in patients with locally advanced colon cancer treated with neoadjuvant chemotherapy." (PMID 35582589, 2019). "This is in agreement with our previous study analyzing EGFL7 expression in 126 patients with stage II-IV colon cancer." (PMID 35582589, 2019). "The aim was to analyze the relationship between miRNA-126 and EGFL7 and disease recurrence in patients with locally advanced colon cancer treated with neoadjuvant chemotherapy." (PMID 35582589, 2019). "PF could effectively reduce the expression of EGFL7 in colon cancer cells, further inhibit the proliferation, invasion, migration, and clone formation, and promote the apoptosis of colon cancer cells." (PMID 36072982, 2022). "Moreover, the results of the RT-qPCR showed that the mRNA content of EGFL7 was significantly higher in colon cancer patients than in normal colonic tissue." (PMID 36072982, 2022). "In conclusion, miRNA-126 and EGFL7 are predictive of disease recurrence in patients with locally advanced colon cancer treated with neoadjuvant chemotherapy and may be instrumental in the identification of patients to be spared of adjuvant chemotherapy." (PMID 35582589, 2019). "Moreover, the expression of EGFL7 is closely related to the prognosis of colon cancer patients." (PMID 36072982, 2022). "The results showed that EGFL7 expression was significantly higher in colon cancer cells than in normal colon cells HIEC-6, wherein the EGFL7 expression in colon cancer cells ranging from low to high was HCT-116, HCT-8, LOVO, and SW480, respectively." (PMID 36072982, 2022). "We further studied the effects of EGFL7 on the proliferation, migration, invasion, and clone formation of colon cancer cells LOVO and SW480 by silencing EGFL7." (PMID 36072982, 2022). "At present, the research on EGFL7 mostly focuses on angiogenesis and cancer cell invasion and metastasis, and there is no research on EGFL7 in colon cancer." (PMID 36072982, 2022). "However, EGFL7 has not been reported in the invasion and metastasis of colon cancer cells." (PMID 36072982, 2022).
pituitary adenomas (5 papers, 2019 to 2024). "Epidermal growth factor-like domain multiple 7(EGFL7) has a higher level of cytoplasmic expression in invasive growth hormone–secreting pituitary adenomas, and is positively correlated with Notch2 and Dll3 in knockdown experiments on GH3 cells." (PMID 30733705, 2019). "Studies have demonstrated that epidermal growth factor‐like domain 7 (EGFL7) is widely involved in GHPAs (hormone‐producing pituitary adenomas) angiogenesis, tumor growth, invasion, and metastasis and inhibits GHPAs growth and invasion by decreasing the expression of this molecule." (PMID 38738958, 2024). "Egfl7 could also promote pituitary adenomas proliferation and invasion via the Notch2/DLL3 signaling pathway." (PMID 37480091, 2023). "Similar results were obtained in another study, which showed higher expression levels of EGFL7 and P‐EGFR in invasive growth hormone‐secreting pituitary adenomas than in noninvasive GHPA (growth hormone‐producing pituitary adenomas)." (PMID 38738958, 2024).
breast carcinoma (4 papers, 2013 to 2024). "Zhang and coworkers have demonstrated that miR-126 is downregulated through the methylation of its host gene, EGFL7, in breast cancer." (PMID 38445462, 2024).
leukemia (4 papers, 2007 to 2024). A malignant (clonal) hematologic disorder, involving hematopoietic stem cells and characterized by the presence of primitive or atypical myeloid or lymphoid cells in the bone marrow and the blood. "DMRs were highly patient-specific, with only 89 genes containing DMRs in all three patients; however, this set included genes involved in leukemia, hematopoiesis, and multipotency, such as FLI1, EGFL7, and TCF15.36–40 We then analyzed the genomic features associated with DMRs across our cohort." (PMID 39553934, 2024).
malignant glioma (4 papers, 2018 to 2022). A grade III or grade IV glioma arising from the central nervous system. "In an attempt to improve the efficacy of VEGF inhibitors in blocking angiogenesis in malignant glioma, we explored the therapeutic potential of EGFL7 and miR‐126/126* in this context." (PMID 30065025, 2018). "We conclude from our study that a combinatorial regimen of anti‐EGFL7 together with the angiogenesis inhibitor anti‐VEGF and the chemotherapeutic agent temozolomide may serve as a novel treatment option for patients suffering from malignant glioma." (PMID 30065025, 2018).
osteosarcoma (4 papers, 2018 to 2024). A usually aggressive malignant bone-forming mesenchymal neoplasm, predominantly affecting adolescents and young adults. "Even though research supports EGFL7 as a potential prognostic marker for the diagnostics and therapeutics of osteosarcoma, few studies have explored the underlying mechanism of EGFL7 in osteosarcoma." (PMID 29363485, 2018). "However, to our knowledge, few reports have explored the underlying mechanism of EGFL7 in osteosarcoma." (PMID 29363485, 2018). "In other cell types, such as the human osteosarcoma, where EGFL7 is highly expressed in tumor cells even more so than in ECs, chemotherapy reduced EGFL7 expression." (PMID 33804387, 2021). "Our previous study found a correlation between EGFL7 expression with clinicopathological features of osteosarcoma." (PMID 32117731, 2020). "Even though few studies explain the relationship between osteosarcoma, EGFL7, and PI3K-Akt, the association of EGFL7 with PI3K-Akt has been established in other types of tumors." (PMID 29363485, 2018). "The results revealed that EGFL7 was expressed in all five cell lines, and the comparison with NHOst revealed that EGFL7 expression increased in all four osteosarcoma cell lines." (PMID 29363485, 2018). "Hence, owing to the clinical correlation of EGFL7 with osteosarcoma and its target potential for therapy, its mechanism is worth further research." (PMID 29363485, 2018). "Hence, whether EGFL7 affects the growth and metastasis of osteosarcoma through the PI3K-Akt signaling pathway and VEGF remains unclear." (PMID 29363485, 2018). "Genes such as EGFL7 and VEGF were differentially expressed in osteosarcoma, and NR4A1 was found to play a key role in osteosarcoma pathophysiology." (PMID 39324133, 2024). "Considering the aberrant secretion of EGFL7 in osteosarcoma (OS) has not yet been elucidated, this study investigated the secretion of EGFL7 in OS and the changes in its secretion after chemotherapy." (PMID 32117731, 2020). "Furthermore, overexpressed EGFL7 activates the RAS-MAPK and PI3K-Akt signaling pathways, which, in turn, regulate the pathological development of osteosarcoma according to clinical and laboratory reports." (PMID 29363485, 2018). "Furthermore, despite a similar gene level of EGFL7 in all four osteosarcoma cell lines, U2OS exhibited a relatively higher trend for the EGFL7 expression." (PMID 29363485, 2018).
pancreatic carcinoma (4 papers, 2017 to 2022). "High expression levels of EGFL7 were significantly correlated with clinicopathologic factors epithelial ovarian cancer and pancreatic carcinoma." (PMID 32117731, 2020). "Several reports have determined that the proliferation and cell-cycle distribution of human pancreatic cancer cells, human choriocarcinoma cells, and renal cell carcinoma are not affected by EGFL7." (PMID 29363485, 2018).
prostate carcinoma (4 papers, 2015 to 2023). A carcinoma that arises from epithelial cells of the prostate gland. "Recently, reduced EGFL7 and miR-126 expression regulated via DNA hypermethylation of the promoter region was observed in ovarian cancer, prostate cancer and malignant pleural mesothelioma." (PMID 35494025, 2022). "miR-126 assists its host gene EGFL7 in inhibiting prostate cancer invasion and metastasis." (PMID 37978168, 2023). "MiR-126 is located in intron 7 of the epidermal growth factor-like protein 7 gene (EGFL7) on chromosome 9, and is down regulated in various cancer types including breast, gastric, and prostate cancer, and RCC." (PMID 26416448, 2015).
endothelial dysfunction (3 papers, 2021 to 2022). In vascular diseases, endothelial dysfunction is a systemic pathological state of the endothelium (the inner lining of blood vessels) and can be broadly defined as an imbalance between vasodilating and vasoconstricting substances produced by (or acting on) the endothelium. "Altered EGFL7 expression is associated with abnormal placentation and systemic maternal endothelial dysfunction, observed in PE." (PMID 35054845, 2022). "In the maternal circulation, endothelial dysfunction and abnormal hemodynamic state are associated with increased levels of EGFL7, which return to control levels after NO treatment." (PMID 35054845, 2022). "When fetal/placental alterations are associated to systemic endothelial dysfunction and multiorgan damage, as in the case of women developing PE, EGFL7 in maternal blood becomes significantly increased." (PMID 34504270, 2021). "Our results also show that ECs compensate for increasing EGFL7 to counteract ICAM and VCAM in the hypertrophic stage; nevertheless, chronic pressure overload leads to endothelial dysfunction, further resulting in less sufficient EGFL7 production." (PMID 35721105, 2022).
heart failure (3 papers, 2022 to 2023). Inability of the heart to pump blood at an adequate rate to meet tissue metabolic requirements. "Knockdown of EGFL7 in TAC mice was associated with deterioration of heart failure, thus indicating the protective role of EGFL7." (PMID 35721105, 2022). "We obtained the following principal findings: 1) There was differential expression of EGFL7 through hypertrophy to heart failure." (PMID 35721105, 2022). "In conclusion, we identified that EGFL7 plays an essential role in pressure overload-induced cardiac remodeling and heart failure." (PMID 35721105, 2022). "We want to explore the role EGFL7 plays during heart failure progression." (PMID 35721105, 2022). "Few previous studies have shown the relevance of EGFL7 in hypertrophy and heart failure." (PMID 35721105, 2022). "The next step was to determine what role EGFL7 plays during heart failure progression." (PMID 35721105, 2022). "In decompensated heart failure, EGFL7 decreased to baseline." (PMID 35721105, 2022). "As inflammation plays a vital role in heart failure, we hypothesized that EGFL7 is protective in pressure overload-induced hypertrophy and the heart failure model TAC." (PMID 35721105, 2022). "However, only SDSL showed an AUC value greater than 0.7 in the test set, whereas EGFL7, SMTNL2, MFAP4, TAGLN, SGPP2 and SMTNL2 showed AUC values greater than 0.5, so SDSL may be a high risk factor in patients with heart failure." (PMID 38250028, 2023). "However, it is unclear whether there is a link between abnormal EGFL7 expression and inflammation in overload stress-induced heart failure." (PMID 35721105, 2022). "The analysis revealed that heart failure samples had significantly higher expression levels of EGFL7, SDSL, PPP1R13l, SMTNL2, MFAP4, and TAGLN genes, which may promote the development of heart failure." (PMID 38250028, 2023). "The link between EGFL7 and inflammation in pressure overload-induced heart failure has not been studied." (PMID 35721105, 2022). "Our results showed that EGFL7 transiently increased during the early 4 weeks of TAC and in hypertensive patients without heart failure." (PMID 35721105, 2022).
metastatic colorectal cancer (3 papers, 2017 to 2023). "The aim of the current study was to investigate the possible prognostic impact of circulating EGFL7 (cir-EGFL7), combined with single nucleotide polymorphism (SNP) analyses, in patients with metastatic colorectal cancer (mCRC) treated with first line chemotherapy and bevacizumab." (PMID 28539619, 2017).
ovarian carcinoma (3 papers, 2022 to 2024). A malignant neoplasm originating from the surface ovarian epithelium. "Survival analysis performed for the entire cohort showed that the epithelial ovarian cancer patients having tumors with high EGFL7 expression had a poorer DFS but similar OS to those with low EGFL7 expression." (PMID 35630004, 2022). "EGFL7 expression has been previously analyzed in one study on human ovarian cancer tissue samples derived from 177 patients." (PMID 35630004, 2022). "Interestingly, our study supports the suggestion that EGFL7 expression is frequent in epithelial ovarian cancers as we detected EGFL7 mRNA transcripts in 13 of 59 (22.03%) HGOSC cases." (PMID 35630004, 2022).
renal carcinoma (3 papers, 2018 to 2021). A carcinoma arising from the epithelium of the renal parenchyma or the renal pelvis. "LncRNA URRCC facilitates proliferation and metastasis of renal cancer by regulating the EGFL7/P-AKT/FOXO3 signaling pathway and indicates poor survival in patients." (PMID 34322379, 2021). "Altogether, our data suggested that URRCC could enhance renal cancer cell proliferation and invasion through EGFL7/P-AKT/FOXO3 signaling." (PMID 30953521, 2019).
renal cell carcinoma (3 papers, 2018 to 2023). "It has been reported that LncRNA HOTAIR regulates renal cell carcinoma angiogenesis through the miR‐126/EGFL7 axis." (PMID 37904709, 2023).